ZNF521 (zinc finger protein 521)
Diseases named in the same sentence as ZNF521 in open-access papers (continued):
Sharing a sentence is not in itself a finding about the gene and the disease.
cancer (16 papers, 2015 to 2025). A tumor composed of atypical neoplastic, often pleomorphic cells that invade other tissues. "miRNA expression profiling tools are currently identifying a multitude of miRNAs, involved together with oncogenes and TFs in the regulation of oncogenesis, including ZNF521, which may be candidates for diagnostic and prognostic biomarkers of cancer." (PMID 34445164, 2021). "Thus, ZNF521 may act usually as a promoter or occasionally as a suppressor of transcription and cancer risk depending on the tissue and the cellular context." (PMID 39025327, 2024). "Malate dehydrogenase, hepatoma‐derived growth factor, Vinculin, Zinc finger protein 521, and neural cell adhesion molecule L1 contribute to cancer cell proliferation and growth." (PMID 39801758, 2025). "ZNF521 can enhance cellular proliferation in different tissues, reduce the cellular differentiation of neural and bone stem cells, and augment stem- and cancer stem-cell compartments." (PMID 37834202, 2023). "ZNF521 is a well-known co-transcriptional factor involved in the homeostasis of normal, cancer and stem cell compartments." (PMID 37834202, 2023). "ZNF521 acts via multiple molecular interactions to control the homeostasis of the immature cell compartment in different tissues and in cancers." (PMID 37834202, 2023). "The authors also revealed that miRNA‐204‐5p, which is commonly downregulated in cancers, is a negative regulator of ZNF521 expression." (PMID 36397644, 2023). "In this study, we found that ZNF521 is a valuable prognostic biomarker that is significantly correlated with cancer immune infiltration." (PMID 36311294, 2022). "Together, these findings suggest that ZNF521 is a valuable prognostic biomarker for gastric and other cancers that is significantly correlated with immune infiltration." (PMID 36311294, 2022). "The expression of ZNF521/zfp521 can also be controlled by miRNAs in several different cancers, where miRNA expression is inversely correlated with that of ZNF521." (PMID 34639154, 2021). "Taken together, ZNF521 can be considered as a cancer-related gene which is aberrantly expressed in MLL-rearranged AML and involved in the induction of B-cell lymphomagenesis." (PMID 34445164, 2021). "Integrated analysis of high-throughput systems revealed a close functional inverse relationship between the specific miRNAs and ZNF521 expression levels comparing cancers and controls." (PMID 34445164, 2021). "Additionally, vinculin, zinc finger protein 521, and neural cell adhesion molecule L1 are known to play roles in cancer development, proliferation, and metastasis, and underscored significant elevation in expression levels as well." (PMID 39801758, 2025). "There exists growing evidence on the regulation of ZNF521 in several cancers, and the recent advances in folate–miRNA relationships could possibly provide additional mechanistic explanation of our finding in future studies." (PMID 39025327, 2024). "Zinc finger protein 521 (ZNF521), which is a transcription co‐factor, has a variety of functions in multiple cells, including hematopoietic, osteo‐adipogenic, neural progenitor, and cancer cells." (PMID 36397644, 2023). "Such a role of ZNF521 in hOC may be exerted via the modulated expression of several regulatory genes which are relevant in cancer." (PMID 36191006, 2022). "Forced ZNF521 expression altered the transcriptional profile of a total of 1375 and 742 genes in HeyA8 and in ES-2 human OC cell lines, respectively, as well as the enrichment of several cancer-related hallmarks including EMT regulatory genes." (PMID 36191006, 2022). "In addition to the role for ZNF521 in cell fate determination in different types of progenitor cells, this TF also plays a crucial role in cancer malignancies." (PMID 34445164, 2021).
cancer (continued). "This affected 17/333 pathway-associated genes including six known cancer genes (HNRNPA2B1, STAG2, TCF7L2, SUZ12, CLTC, and ZNF521), Thus, the integration procedure prioritized specific pathway-related genes compared to their original rankings in individual mutation datasets." (PMID 32024846, 2020). "Therefore, we hypothesized that ZNF521 may promote cancer progression via suppression of EBF1 activity in GC." (PMID 36397644, 2023). "Our current study identified the ZNF521/EBF1/AKR1B1 axis, which is hyperactivated in GC and plays important role in promoting cancer cell growth, migration, and invasion." (PMID 36397644, 2023). "The human zinc finger protein 521 (ZNF521) is a co-transcriptional factor with multiple recognized regulatory functions in a range of normal, cancer and stem cell compartments." (PMID 37834202, 2023). "Moreover, ZNF521 knockdown‐mediated elevation of EBF1 expression resulted in downregulation of AKR1B1 and subsequent inhibition of cancer cell proliferation, migration, and invasion." (PMID 36397644, 2023).
infection (1 paper, 2014). The state of being infected such as from the introduction of a foreign agent such as serum, vaccine, antigenic substance or organism. "Western blotting analyses confirmed the strong expression of EGFP and highlighted a more abundant production of ZNF521 in all cells transduced with UMG-LV11-ZNF521 than in those infected with UMG-LV5-ZNF521, despite the reduced infection rate." (PMID 25502183, 2014).
ZNF521 also shares sentences with these, for which no sentence is quoted: hepatocellular carcinoma (2 papers); Alzheimer disease (1); bladder transitional cell carcinoma (1); colon adenocarcinoma (1); colon cancer (1); esophageal SCC (1); hematological malignancy (1); invasive bladder transitional cell carcinoma (1); liver cancer (1); lung carcinoma (1); lung squamous cell carcinoma (1); lymph node metastasis (1); Lymphatic Metastasis (1); lymphoid leukemia (1); lymphoid tumors (1); multiple myeloma (1); myeloid tumors (1); neuroblastoma (1); oral cancer (1); osteoporosis (1); ovarian endometriosis (1); thyroid cancer (1).